DUSP1 (dual specificity phosphatase 1)
Diseases named in the same sentence as DUSP1 in open-access papers (continued):
Sharing a sentence is not in itself a finding about the gene and the disease.
prostate carcinoma (continued). "These tumors are generally found in older men, and DUSP1 expression is associated with PCa suppression, and an inverse correlation was reported between DUSP1 expression and activation of p38 MAPK and p65/NF-κB in human prostate cancer tissue specimens." (PMID 41158869, 2025). "USP33 directly bound dual specificity protein phosphatase 1 (DUSP1) and reduced its ubiquitination, thereby impairing JNK activation and apoptosis in prostate cancer." (PMID 39694539, 2025). "In prostate cancer, DUSP1 efficiently dephosphorylated JNK 11; in hepatocellular carcinoma, DUSP1 mainly inhibits the p38/MAPK pathway 12; and in this study, DUSP1 deficiency promoted EC progression via the ERK/MAPK pathway." (PMID 37057290, 2023). "The results showed that silencing the expression of DUSP1 and TNFSF9 promoted the growth and proliferation of the prostate cancer PC3 cells." (PMID 36142828, 2022). "We also observed high DUSP1 mRNA levels in PC3 cells, a prostate cancer cell line shown to have low levels of LINE-1 expression." (PMID 34425899, 2021). "Dual specificity phosphatase 1 (DUSP1) acts as a tumor suppressor by negatively regulating MAPK activity in different tumors, including prostate cancer." (PMID 33800291, 2021). "Since we observed a differential expression of DUSP1, Snail, and the active forms of JNK and ERK in samples from prostate cancer patients at different stages, we next studied the interrelation between the levels of these proteins and some of the most important clinical parameters." (PMID 33800291, 2021). "Interestingly, we also demonstrate a correlation between the expression levels of DUSP1 and Snail and the activity of JNK and ERK in samples from prostate cancer patients, discovering a novel approach to predict the prognosis and outcome of this disease." (PMID 33800291, 2021). "In addition, our results strongly suggest that the induction of DUSP1 or the inhibition of ERK and JNK pathways could be useful as a therapeutic approach to treat prostate cancer." (PMID 33800291, 2021). "Given that DUSP1 impaired the activity of JNK and ERK, and that the individual inhibition of these MAPKs downregulated Snail expression, as well as cell migration and invasion, we further studied whether these MAPKs cooperated in the regulation of these events in our prostate cancer cells." (PMID 33800291, 2021).
asthma (23 papers, 2011 to 2025). "In particular, the role of DUSP1 has been emphasized in airway inflammatory diseases (e.g. asthma or chronic obstructive pulmonary diseases), where glucocorticoids are the primary choice of treatment for acute exacerbated states." (PMID 35488446, 2022). "In alveolar macrophages from patients with glucocorticoid-resistant asthma, the expression of DUSP1 in response to glucocorticoids was reported to be reduced and, correspondingly, p38 MAPK phosphorylation was increased." (PMID 21547253, 2011). "Asthma pathogenesis engages mitogen-activated protein kinase (MAPK) inflammatory pathways, counterregulated by dual-specificity phosphatase-1 (DUSP1)." (PMID 41246337, 2025). "Their research suggests that let-7i-5p in PM2.5-EVs activates the MAPK signaling pathway by inhibiting the dual specificity phosphatase 1 (DUSP1) gene, thereby exacerbating PM2.5-induced asthma." (PMID 39273095, 2024). "In total, 6 genes were upregulated (e.g. CCL3L1, CCL4L2, GPR82) and 20 were downregulated (e.g. JUN, IFITM3, DUSP1, GNG7) in peripheral eosinophils of COPD patients compared to asthma." (PMID 39422548, 2024). "Furthermore, in macrophages from patients with severe asthma, the activity of p38 was increased while expression of MKP-1 (DUSP1) was reduced." (PMID 29033931, 2017).
hepatocellular carcinoma (23 papers, 2010 to 2025). A malignant tumor that arises from hepatocytes. "Lower DUSP1 expression was noted in hepatocellular carcinoma (HCC) tumors in comparison to normal liver tissues." (PMID 41158869, 2025). "In hepatocellular cancer cells, DUSP1 expression inversely correlates with phosphorylated ERK and cell proliferation." (PMID 38612874, 2024). "DUSP1 (an anti-apoptotic phosphatase) functions as a tumor suppressor in hepatoma cells and is also a negative regulator of AKT activation." (PMID 35935969, 2022). "DUSP1 was found to promote carcinogenesis in prostate and pancreatic cancers, but inhibit carcinogenesis in hepatocellular carcinoma." (PMID 28129656, 2017). "An earlier study showed that, in hepatocellular carcinoma, levels of DUSP1 expression correlate inversely with those of phosphorylated ERK, as well as with the proliferation index and microvessel density." (PMID 28129656, 2017). "While in liver carcinoma, DUSP1 impacted the p38/MAPK pathway." (PMID 40535772, 2025). "Lately, Gu and co-authors discovered that MSCs-derived exosome could suppress hepatocellular cancer stem cells (CSCs) malignancy through a long noncoding RNAs (lncRNAs) C5orf66-AS1/micro-RNA-127-3p/dual-specificity phosphatase 1 (DUSP1)/ERK axis." (PMID 37849741, 2023). "Interestingly, strong expression of DUSP1 is a favorable prognostic factor in glioma and hepatocellular carcinoma." (PMID 36812479, 2023). "A related study reported that DUSP1 remarkably suppresses the invasion and metastasis of hepatocellular carcinoma (HCC) cells." (PMID 35911442, 2022). "The expression of DUSP1 in hepatocellular carcinoma (HCC) decreased slightly compared with normal liver tissues." (PMID 27227569, 2016). "Conversely, in hepatocellular carcinoma (HCC) increased DUSP1 levels correlate with better prognosis." (PMID 24409315, 2014). "Functional studies revealed that DUSP1 reactivation led to the suppression of ERK1/2–SKP2–CKS1 activity, inhibition of proliferation, and induction of apoptosis in human hepatoma cell lines 7703, HuH7, SNU-182, and SNU-387." (PMID 40943262, 2025). "Concerning hepatocellular carcinoma (HCC), accumulating evidence indicates that DUSP1 may counteract tumourigenesis, making it a possible target in this neoplasm." (PMID 40943262, 2025).
depression (22 papers, 2013 to 2025). "It was found that Fos and Dusp1 were the mRNAs for biopsychological stress marker genes associated with major depression." (PMID 37905694, 2024). "Dusp1 is also overexpressed in models of depression caused by chronic pain, and mild, unpredictable, and periodic photostimulation." (PMID 37340011, 2023). "Overexpression of Dusp1, linked to a depressive-like phenotype, is a common feature of various rodent chronic-stress-based models of depression." (PMID 37340011, 2023). "A few DUSPs appeared to be dysregulated in major depressive disorder by microarray analysis, wherein, the pathogenic role of DUSP1 in depression was further confirmed." (PMID 28902166, 2017). "In this study, the present findings reveals that the expressions of ULK1, MAPK14, WIPI1, and DUSP1 were associated with the immune system, thereby participated in the pathogenesis of depression and could provide potential targets for future treatments." (PMID 41311024, 2025). "Overexpression of Dusp1 is vital to the physiology of stress and linked to a depressive‐like phenotype, which is a common feature of various rodent chronic‐stress‐based models of depression." (PMID 37905694, 2024). "Through the PPI network we found that the potential targets of ZZCD for the treatment of anxiety and depression are Fos, Nr4a1, Dusp1, Junb, and Egr2." (PMID 37905694, 2024). "Dusp1 appears especially important, as its role in the pathogenesis of depression has been demonstrated both in various animal models of depression and in patients with depressive disorders." (PMID 37340011, 2023). "Previously, the significance of altered Dusp-1 was tested in rodent models of depression and it was demonstrated that increased central Dusp-1 expression, as a result of stress or viral-mediated gene transfer, causes depressive behaviors." (PMID 33327458, 2020). "For instance, DUSP2 has previously been identified to link stress experience and depression pathogenesis: DUSP1 and DUSP2 expression was increased in response to chronic stress in rodents and in the brain of two separate cohorts of depressed patients." (PMID 32839428, 2020). "In terms of pathophysiology, an important observation was that DUSP1/MKP-1 levels were elevated in the hippocampal region of post-mortem brain from patients who had been diagnosed with major depressive disorder (MDD)." (PMID 30401534, 2019). "In agreement, lack of the DUSP1 protein protects from depressive behaviour, indicating that inhibition of DUSP1 activity can be a promising therapeutic approach for the treatment of depression." (PMID 31018603, 2019). "The first attempt to assay DUSP1 inhibitors in the treatment of depression focused on Sanguinarine, a natural plant-derived alkaloid with the capacity to selectively inhibit DUSP1." (PMID 31018603, 2019). "The decreased expressions of mRNAs in CUMS-induced depression mice include Slc6a11, Hap1, Gad1, Gad2, Gng4, Slc32a1, Doc2g, Slc32a1, Magel2, Prkcd, Ngfr, Dusp1, Th, Itih3, Cacna2d2, Arc, Mbp, Peg10, Fos, and so on." (PMID 27427907, 2016). "DUSP1 overexpression also appears to be involved in depression." (PMID 37340011, 2023). "DUSP1 gene may be a representative of a promising new drug target for the treatment of depression and other mood disorders." (PMID 35566012, 2022). "Therefore, Dusp-1 is representative of promising new drug targets for the treatment of depression and other mood disorders." (PMID 33327458, 2020). "Overexpression of DUSP1 has been observed in postmortem brain tissues of MDD patients, suggesting its potential role in the pathophysiology of depression." (PMID 41311024, 2025). "DUSP1 expression in the blood of patients with MDD is reduced after transcranial magnetic stimulation, a treatment that also alleviates symptoms of depression." (PMID 37340011, 2023).
depression (continued). "Some of the common down genes in maternal C57 mice and depression were for the MAP kinase pathway and some of the common down genes included: FOS, EGR1, DUSP1, BDNF, NR4A1, NR3C1, the neuropeptide somatostatin (SST), and one of the its receptors, SSTR2." (PMID 34997033, 2022). "Kruppel-like factor-4 (Klf-4) and dual-specificity phosphatase-1 (Dusp-1) are known to be negative regulators of the mitogen-activated protein kinase (MAPK) cascade, and the function of this cascade decreases in depression." (PMID 33327458, 2020).
pancreatic cancer (22 papers, 2006 to 2025). "Intriguingly, DUSP1 has been identified as a ferroptosis inhibitor in pancreatic cancer, where it blocks lipid peroxidation-dependent ferroptosis." (PMID 40823304, 2025). "In pancreatic cancer, DUSP1 is a novel target for enhancing cell sensitivity to gemcitabine, a common chemotherapy drug." (PMID 40361912, 2025). "Researchers have found that DUSP1 can inhibit autophagy-dependent ferroptosis in human pancreatic cancer cells." (PMID 36585417, 2022). "For example, DUSP1 expression is increased in pancreatic cancer and shown that its downregulation leads to reduced tumorigenicity." (PMID 25568665, 2014). "Yet, DUSP1 is overexpressed in pancreatic cancer cells (PCCs) in PDAC where it paradoxically enhances colony formation in soft agar and promotes in vivo tumorigenicity." (PMID 24409315, 2014). "Using a doxycycline-inducible strategy to suppress DUSP1 in established orthotopic pancreatic tumors, we show that combining gemcitabine with DUSP1 inhibition prolongs survival, attenuates angiogenesis, and enhances apoptotic cell death." (PMID 24409315, 2014). "Our use of immune deficient mice precludes an assessment of the consequence of DUSP1 inhibition on the immune system or on macrophage number and activation within the pancreatic tumor mass." (PMID 24409315, 2014). "In pancreatic cancer, DUSP1 is overexpressed and promotes proliferation and tumor growth." (PMID 41158869, 2025). "Moreover, DUSP1 knockdown increases ferroptosis activator expression in pancreatic cancer cells by enhancing lipid peroxidation, and DUSP1 is involved in lipid peroxidation and ferroptotic cell death by inducing autophagy." (PMID 41158869, 2025). "Also, DUSP1 sensitizes non-small cell lung cancers and pancreatic cancers to chemotherapy, but it promotes chemoresistance in breast and ovarian cancers." (PMID 31086176, 2019). "In pancreatic cancer, DUSP1 decreases tumor cell proliferation by inhibiting the MAPK/ERK pathway." (PMID 29383165, 2017). "Knocking down DUSP1 in pancreatic cancer cells attenuated the tumorigenicity in a nude mouse model." (PMID 27227569, 2016). "Taken together, these results suggest that interrupting the negative feedback on p38 MAPK and JNK signaling by suppressing DUSP1 could enhance apoptosis and improve the chemosensitivity of pancreatic cancer to multiple chemotherapeutic agents." (PMID 24409315, 2014). "Using doxycycline-inducible knockdown of DUSP1 in established orthotopic pancreatic tumors, in the present study we determined that combining gemcitabine with DUSP1 inhibition prolonged animal survival and enhanced apoptotic cell death, compared with gemcitabine alone." (PMID 24409315, 2014). "Using doxycycline-inducible knockdown of DUSP1 in established orthotopic pancreatic tumors, we found that combining gemcitabine with DUSP1 inhibition improves animal survival, attenuates angiogenesis, and enhances apoptotic cell death, as compared with gemcitabine alone." (PMID 24409315, 2014). "Furthermore, DUSP1 inhibition augmented pancreatic cancer cell sensitivity to gemcitabine." (PMID 41158869, 2025). "Moreover, DUSP1 targeting leads to increased levels of p-ERK1 and p-ERK2, and ERK activation in pancreatic cancer cells enhances gemcitabine chemoresistance." (PMID 24409315, 2014). "We therefore surmised that a dual-specificity MAPK phosphatase, MKP-1/DUSP1, a representative mediator of dexamethasone's anti-inflammatory effects, could be the link between dexamethasone and the JNK pathway in CSC regulation in pancreatic cancer." (PMID 33115754, 2020).
Sepsis (21 papers, 2009 to 2026). Sepsis is defined as life-threatening organ dysfunction caused by a dysregulated host response to infection. "Differences between DUSP4/MKP-2 and DUSP1/MKP-1 were further underlined in studies of the response of DUSP4−/− mice to experimental LPS-induced sepsis." (PMID 30401534, 2019). "reuteri and its metabolite IAld exert a protective effect against sepsis through the DUSP1/ERK/NOX2/ROS axis, providing novel mechanistic insights and potential therapeutic targets for immunometabolic intervention in sepsis." (PMID 42135927, 2026). "Hypaphorine demonstrates anti‐inflammatory effects in sepsis‐induced acute lung injury by modulating the DUSP1/p38/JNK signalling pathway." (PMID 41170413, 2025). "To further validate the association of Dusp1 with myocardial injury, we utilized the GSE65682 dataset, a sepsis cohort sequencing dataset with 28-day survival data." (PMID 39659576, 2024). "In the context of infectious diseases and sepsis, studies on the role of DUSP1 have focused on macrophage responses." (PMID 36985341, 2023). "DUSP1 is a critical negative regulator of pathological inflammatory responses in experimental models of sepsis or endotoxic shock." (PMID 26019272, 2015). "In addition, we constructed a Cox proportional hazard model using MAPK14, VEGFA, TGFBR1, and DUSP1: they influenced survival within 28 days in sepsis patients, which emphasizes their importance in sepsis pathogenesis." (PMID 36188533, 2022). "We identified four ferroptosis-related genes (MAPK14, VEGFA, TGFBR1, DUSP1) that may influence the pathological progression of sepsis and the resulting organ dysfunction." (PMID 36188533, 2022). "Findings from those studies are consistent with our prediction that XIST−hsa-let-7b-5p−TGFBR1/DUSP1 may be a vital ceRNA regulatory network in sepsis." (PMID 36188533, 2022). "Among the upregulated DEGs in E-SEP compared to Y-SEP, we observed inflammation-associated genes, such as FOSB, DUSP1, and JUNB, and aging-associated genes, such as IFN-stimulated genes DDIT4 and DUSP2, thereby indicating an overactive inflammatory response of cDCs in elderly patients with sepsis." (PMID 38909272, 2024). "Considering the importance of this pathway for sepsis and ferroptosis, we chose these key ferroptosis-related DEGs for subsequent analyses: MAPK14, VEGFA, TGFBR1, and DUSP1." (PMID 36188533, 2022). "Two murine sepsis models revealed that DUSP4 is a positive regulator of inflammation, in contrast to the closely related DUSP1/MKP-1." (PMID 31159473, 2019). "As these results indicate an indirect phenotypic effect of the DUSP4 knockout, the combined deletion of both DUSP1 and DUSP4 is desirable to study DUSP redundancy and combinatorial effects during sepsis and inflammation." (PMID 31159473, 2019). "The results indicated that 8 genes (MAPK14, MAPK8, TLR4, MAP3K5, CYBB, DUSP1, MAPK1 and ATM) might be closely related to the occurrence of sepsis." (PMID 36117534, 2022). "We predicted that the XIST−hsa-let-7b-5p−TGFBR1/DUSP1 ceRNA network and transcription factor E2F1 might be important regulators of sepsis." (PMID 36188533, 2022). "Previous results showed that DUSP1 was an important negative feedback molecule limiting the proinflammatory response in the heart during sepsis." (PMID 32448150, 2020). "DUSP proteins regulate inflammatory responses and mice lacking DUSP1 have increased cytokine expression and increased sepsis in response to endotoxin." (PMID 27088599, 2016). "The boxplot revealed 26 differentially expressed genes between the sepsis-induced ALI and control samples: Ncf2, Slc2a6, Cd44, Txnip, Slc2a1, Ubc, Hspb1, Zfp36, Arntl, Ddit4, Tnfaip3, Txnrd1, Mt1, Hmox1, Gch1, Gclc, Stat3, Egfr, Hif1a, Bach1, Socs1, Dusp1, Cdkn1a, Fth1, Steap3, and Alox12." (PMID 37081490, 2023). "No studies have shown that MAPK14, VEGFA, TGFBR1 and DUSP1 regulate ferroptosis in sepsis." (PMID 36188533, 2022).
non-small cell lung carcinoma (19 papers, 2010 to 2025). A group of at least three distinct histological types of lung cancer, including non-small cell squamous cell carcinoma, adenocarcinoma, and large cell carcinoma. "Overexpression of DUSP-1 has been reported to decrease the growth rate, the invasion and migration capacities of non-small cell lung cancer cells and thus inhibit bone metastasis." (PMID 37160873, 2023). "Gene expression profile in non-small-cell lung cancer (NSCLC) H460 cells after silencing DUSP1 revealed that the knockdown of DUSP1 modulates MAP kinase phosphatase activity, cell-cell signaling, growth factor, tyrosine kinase receptor activity, and angiogenesis." (PMID 41158869, 2025). "Some studies have shown the aberrant expression status of DUSP1 in malignant tumours such as prostate small cell carcinoma, liver cancer, and non-small cell lung cancer, which may affect the therapeutic effect of chemotherapeutic drugs." (PMID 35911442, 2022). "Indeed, the overexpression of DUSP1 rendered non-small cell lung carcinoma (NSCLC) H460 cells resistant to cisplatin, while its downregulation sensitized these cells to cisplatin-induced cell death." (PMID 40943262, 2025). "Previous evidence indicates DUSP1/MKP1 overexpression in colon, bladder, and non-small cell lung cancers, where it modulates angiogenesis, invasion, and metastasis." (PMID 40535772, 2025). "DUSP1 is overexpressed in a range of epithelial tumors including PDAC, non-small-cell lung cancer, breast, ovarian, gastric, and early-stage prostate cancer, and this overexpression is correlated with poor patient survival in ovarian cancer." (PMID 24409315, 2014). "Downregulation of DUSP1 suppresses the expression of angiogenic factors, such as SH2D2A and VEGF-C in non-small-cell lung cancer (NSCLC) cells, and functional assays have confirmed the role of DUSP1 in promoting tumor angiogenesis." (PMID 24409315, 2014). "In addition, DUSP1/MKP1 was found to promote angiogenesis, invasion and metastasis in non-small-cell lung cancer." (PMID 28129656, 2017).